NTRK2 (neurotrophic receptor tyrosine kinase 2)
Diseases named in the same sentence as NTRK2 in open-access papers (continued):
Sharing a sentence is not in itself a finding about the gene and the disease.
brain tumor (9 papers, 2019 to 2025). "Typically, NTRK fusion events involve the NTRK1 or NTRK3 genes, whereas NTRK2 mutations are more frequently observed in primary brain tumors." (PMID 40647390, 2025). "NTRK2 encodes neurotrophin receptors, which are well known to play a role in brain tumor pathogenesis." (PMID 30991699, 2019).
multiple myeloma (9 papers, 2013 to 2022). "Still, the MATCH basket trial is looking to enroll patients with both solid and liquid malignancies, including multiple myeloma, harboring NTRK1, NTRK2, or NTRK3 gene fusions into the larotrectinib subprotocol (NCT02465060)." (PMID 35127532, 2021).
non-small cell lung carcinoma (9 papers, 2011 to 2025). A group of at least three distinct histological types of lung cancer, including non-small cell squamous cell carcinoma, adenocarcinoma, and large cell carcinoma. "NTRK2 fusion coexisting with EGFR mutations is a rare molecular characteristic of non-small cell lung cancer, accompanied by positive PD-L1 expression, and may serve as a promising biomarker for targeted therapy." (PMID 41383499, 2025).
Ataxia (8 papers, 2013 to 2024). Ataxia refers to impaired coordination of voluntary muscle movement. "Our study allowed us to address this question, demonstrating that Ntrk2 deletion from just a subset of GCs is sufficient to evoke ataxia symptoms." (PMID 39194574, 2024). "To investigate whether abnormal BDNF–TrkB signalling in a subset of GCs is sufficient to evoke ataxia, we used TrkbPenk-KO mice carrying Ntrk2 deletion in their enkephalinergic precursor cells." (PMID 39194574, 2024). "We found that deleting Ntrk2, encoding the TrkB receptor, eventually interfered with PC function, leading to ataxia symptoms in the TrkbPenk-KO mice without affecting their cerebellar morphology or levels of selected synaptic markers." (PMID 39194574, 2024). "Whether the Gabra6-specific deletion of Ntrk2 would lead to ataxia symptoms has not been previously explored." (PMID 39194574, 2024). "Notably, Ntrk2 mutant (Wnt1Cre;fBZ/fBZ) mice were ataxic, as seen from the paw print and accelerated rotarod tests, supporting the idea that dysfunctional BDNF–TrkB signalling can contribute to ataxia symptoms." (PMID 39194574, 2024).
pilocytic astrocytoma (8 papers, 2016 to 2026). Pilocytic astrocytoma is a rare subtype of low-grade glioma of the central nervous system characterized by a well circumscribed, often cystic, brain tumor with a discrete mural nodule and long, hair-like projections that extend from the neoplastic astrocytes. "The NACC2-NTRK2 fusion utilized thus far throughout the present work, with exon 4 of NACC2 joined to exon 13 of NTRK2, is known to cause pilocytic astrocytoma." (PMID 38935636, 2024). "In this report, we describe a novel PML-NTRK2 gene fusion occurring in an adult sporadic pilocytic astrocytoma and review the biology and implications of specific NTRK2 mutations occurring in CNS neoplasms." (PMID 32082673, 2020). "NTRK2 has been previously shown to increase metastatic potential by suppressing anoikis and gene fusions involving NTRK2 have been found in pilocytic astrocytoma as well as pontine glioma." (PMID 27672444, 2016). "Activating fusions of NTRK1, NTRK2, or NTRK3 occur in approximately 40% of pediatric high-grade gliomas and NTRK2 fusions in about 3% of pediatric pilocytic astrocytomas." (PMID 32906676, 2020). "Sporadic pilocytic astrocytoma frequently harbors somatic alterations in BRAF, with rare pilocytic astrocytomas containing alterations in FGFR1 and NTRK2." (PMID 32082673, 2020). "A case of a nonresectable pilocytic astrocytoma harboring a novel autophagy related 16 like 1-neurotrophic receptor tyrosine kinase 2 fusion is reported." (PMID 39326005, 2025).
tauopathy (7 papers, 2021 to 2024). Neurodegenerative disorders involving deposition of abnormal tau protein isoforms (tau proteins) in neurons and glial cells in the brain. "In these animals we examined short-term memory and the expression of genes involved in the development of tauopathy (Htr7 and Cdk5), as well as biomarkers of neurodegenerative processes – the Bdnf gene and its receptors TrkB (the Ntrk2 gene) and p75NTR (the Ngfr gene)." (PMID 39027123, 2024).
bladder cancer (6 papers, 2011 to 2023). "Hotspots in NTRK2 or MAPKAPK2 are not present in bladder carcinoma but in other entities (Head-SCC, Lung-AdenoCA and Uterus-AdenoCA)." (PMID 35013316, 2022).
leukemia (6 papers, 2016 to 2024). A malignant (clonal) hematologic disorder, involving hematopoietic stem cells and characterized by the presence of primitive or atypical myeloid or lymphoid cells in the bone marrow and the blood. "Notably, pharmacological inhibition demonstrated that p110α and p110δ are the major isoforms mediating the phosphoinositide 3-kinase/AKT signaling driven by NTRK2 activation in PTEN-deficient leukemia cells." (PMID 27672444, 2016). "Observing the impact of NTRK-2/3 gene alterations at the atomic level could aid in discovering a viable treatment for Trk-related leukemias." (PMID 39119195, 2023). "Researchers may be able to use this information to establish a therapeutic target for NTRK2/3 gene-related leukemia." (PMID 39119195, 2023). "NTRK2 and its ligand, brain-derived neurotrophic factors (BDNF), are co-expressed in acute leukemia blasts and negatively correlate with leukemia patients’ survival." (PMID 34249950, 2021). "Mice with bone marrow transduced with both NTRK2 and BDNF developed AML and T-ALL, suggesting a role of NTRK2 in leukemia pathogenesis." (PMID 27672444, 2016). "NTRK2 and its ligand BDNF have been shown to be co-expressed in acute leukemia blasts, and this negatively correlates with survival of leukemia patients." (PMID 27672444, 2016).
liver fibrosis (6 papers, 2021 to 2026). "Reln was reported to be related to liver fibrosis, and Ntrk2 encodes a tyrosine kinase receptor, TrkB, which is abundantly expressed in lung tissue and responsible for hypoxia, thus promoting the proliferation of pulmonary arterial smooth muscle cells." (PMID 34395518, 2021).
pulmonary fibrosis (6 papers, 2013 to 2022). Chronic progressive interstitial lung disorder characterized by the replacement of the lung tissue by connective tissue, leading to progressive dyspnea, respiratory failure, or right heart failure. "Moreover, the specific increase in the level of the anoikis resistance marker NTRK2 suggested a unique interaction between fibroblasts and ECM during pulmonary fibrosis." (PMID 35216634, 2022).
sarcoma (6 papers, 2008 to 2025). A usually aggressive malignant neoplasm of the soft tissue or bone. "Our case is among the first few in the literature on NTRK2 fusion sarcoma with first-line larotrectinib therapy in the primary and metastatic setting, with good clinical response and minimal side effects." (PMID 37865792, 2023). "The results demonstrate the importance of the identification of NTRK alteration in soft tissue sarcoma, and the urgent need for mechanistic study for resistance to targeted therapy in NTRK2 fusion sarcoma." (PMID 37865792, 2023). "There were two tumors, which demonstrated clear-cut 5′/3′-end NTRK2 (NSCLC) and NTRK3 (adult sarcoma) expression imbalances, but turned out to be NTRK rearrangement-negative by the TruSight RNA Fusion NGS panel." (PMID 37762506, 2023). "Herein, we report the identification of NTRK2 gene rearrangement by initial RNA-based NGS, with the efficacy of larotrectinib treatment in an adult patient with a sarcoma harboring STRN-NTRK2 fusions." (PMID 37865792, 2023).
squamous cell carcinoma (6 papers, 2017 to 2026). A carcinoma arising from squamous epithelial cells. "The association between the presence of NTRK2 and a good prognosis in patients with squamous cell carcinoma may suggest an important role of this gene in the biology of this type of neoplasia." (PMID 35860155, 2022). "NTRK1 and NTRK2 are preferentially expressed in squamous cell carcinoma as compared to other histological types, especially adenocarcinoma." (PMID 35860155, 2022). "The mRNA for TrkB-T1 is the most abundant NTRK2 gene mRNA in all squamous cell carcinomas (SCCs) in the TCGA database." (PMID 31221127, 2019). "While Collagen XXIII expression has already been suggested as potential biomarker for NSCLC, APCDD1L-AS1 expression is of prognostic value in squamous cell carcinoma and NTRK2 has recently been reported as therapeutic target in combination with tyrosine kinase inhibitors in this tumor entity." (PMID 33953302, 2021).
thyroid cancer (6 papers, 2014 to 2025). "No patient in our study cohort had a NTRK2 gene fusion, consistent with the lack of reported cases in thyroid cancer in the literature." (PMID 38329731, 2024). "Notably, thyroid cancers have the highest frequency of recurrent kinase fusions (63/498, 13%), and all fusion events including ALK, BRAF, MET, NTRK1, NTRK2, RAF1 and RET are mutually exclusive in this cancer type." (PMID 25204415, 2014). "In addition, the poorly differentiated thyroid carcinoma presented faint cytoplasmic pan-TRK staining in less than 5% of isolated tumor cells by IHC and negative FISH results for NTRK3, NTRK1 and NTRK2." (PMID 40338900, 2025).
asthma (5 papers, 2020 to 2023). "Plasma BDNF concentrations, as well as BDNF and NTRK2 (TrkB gene) polymorphisms, were investigated in 120 asthma patients and 120 healthy individuals using enzyme-linked immunosorbent assay and polymerase chain reaction, respectively." (PMID 33114368, 2020). "A number of studies thus far have sought to investigate the role of BDNF in the airways by assessing its concentration locally and in the peripheral circulation, as well as by determining the association between selected polymorphisms in the BDNF and NTRK2 (TrkB) genes and the development of asthma." (PMID 33114368, 2020). "Moreover, further research is warranted to better understand the role of peripheral BDNF levels, as well as BDNF and NTRK2 (TrkB gene) polymorphisms, in adult asthma." (PMID 33114368, 2020). "We hypothesized that plasma BDNF concentration would be significantly altered in asthma patients compared to healthy subjects, while BDNF Val66Met and NTRK2 rs1439050 polymorphisms would be associated with asthma, disease severity, and certain asthma phenotypes." (PMID 33114368, 2020). "Some of these sites were associated with offspring outcomes in this cohort including ever-asthma (NTRK2), ever-wheezing (DNAJC14, TPCN1), weight (FAM53B, NTRK2) and BMI (FAM53B, NTRK2) (p < 0.05)." (PMID 37649101, 2023). "Concerning "Workplace full of chemicals or other fumes: Sometimes" (with causal effect on “Condition that has ever been diagnosed by a doctor: Asthma”) the most statistically significant pathway involved is “NTRK2 activates RAC1”." (PMID 36395113, 2022). "Few reports in the literature up to this point have evaluated the possible influence of BDNF and NTRK2 polymorphic variants on serum and plasma BDNF levels in patients with asthma." (PMID 33114368, 2020). "When exploring the biological impact of other genes mapped to the dmCpGs uniquely associated with father’s pubertal smoking, several were related to genes associated with innate immunity, allergic diseases and asthma development, such as TLR9, CSF1R, DNAJ14, NTRK2 and TPCN1." (PMID 37649101, 2023). "Plasma BDNF concentration was not influenced by NTRK2 rs1439050 polymorphism in both healthy subjects and asthma patients." (PMID 33114368, 2020). "The distribution of the NTRK2 rs1439050 genotypes (p = 0.14), alleles (p = 0.07), GG vs. T allele carriers (p = 0.55), and TT vs. G carriers (p = 0.34) was not significantly different between asthma patients with T2-high and T2-low phenotypes." (PMID 33114368, 2020). "The NTRK2 rs1439050 genotype distributions were also in HWE for both the control group (p = 0.34) and the individuals with asthma (p = 0.40)." (PMID 33114368, 2020).
esophageal squamous cell carcinoma (4 papers, 2012 to 2026). Esophageal squamous cell carcinoma (ESCC) is a type of esophageal carcinoma (EC) that can affect any part of the esophagus, but is usually located in the upper or middle third. "With respect to esophageal cancer, NTRK2 was found to have an altered allele frequency in a group of mainly esophageal squamous cell cancers, suggesting a role in esophageal cancer susceptibility and/or development." (PMID 27795744, 2016).
glioneuronal tumor (4 papers, 2017 to 2023). "Surrey reported a case of mixed neuronal-glial tumors (MNGT) with SPECC1L::NTRK2 fusion." (PMID 36531047, 2022). "STRN1::NTRK2 and ARHGEF2::NTRK1 were reported in a single case of malignant glioneuronal tumor, respectively." (PMID 36531047, 2022). "We describe here a novel NTRK2::LHFPL3 fusion in a Dysembryoplastic neuroepithelial tumor (DNT), a low-grade glioneuronal tumor." (PMID 36531047, 2022). "More recently, a novel MC of glioneuronal tumor (called the “glioneuronal tumor, not otherwise specified, subtype A") harboring RTK (ALK, NTRK1, NTRK2, NTRK3, and MET) fusions and MAPK (RAF1) fusions have been isolated by DNA‐methylation profiling." (PMID 37349135, 2023).
Hepatic steatosis (4 papers, 2020 to 2024). Steatosis is a term used to denote lipid accumulation within hepatocytes. "Among downregulated genes (KIT, NTRK2, MAMDC2, and ANXA13), KIT could regulate apoptosis, NTRK2 was revealed that capable of activating apoptosis pathways with Brain derived neurotrophic factor (BDNF), which may promote the progression of fatty liver disease." (PMID 38665091, 2024).
metastatic carcinoma (4 papers, 2016 to 2023). A carcinoma which has spread from the original site of growth to another anatomic site. "The ALKA-372-001, STARTRK-1, and STARTRK-2 studies evaluated both the safety and efficacy of orally administering entrectinib to adult patients with locally advanced metastatic cancer with NTRK1, NTRK2, NTRK3, ROS1, or ALK rearrangements." (PMID 37111737, 2023). "The studies evaluated both the safety and efficacy of orally administering entrectinib to adults with locally advanced metastatic cancer with NTRK1, NTRK2, NTRK3, ROS1, or ALK rearrangements." (PMID 37111737, 2023).
Brain atrophy (3 papers, 2014 to 2022). Partial or complete wasting (loss) of brain tissue that was once present. "As BDNF and NTRK2 play important role in neuronal maintenance and plasticity, identification of this upstream regulator will provide an important insight on molecular mechanism underlying brain atrophy and cell loss observed in the sgACC of MDD." (PMID 35280164, 2022).
Ewing sarcoma (3 papers, 2019 to 2024). A small round cell tumor that lacks morphologic, immunohistochemical, and electron microscopic evidence of neuroectodermal differentiation. "Among pediatrics there was one case each of fibrosarcoma (TPM3::NTRK1), Ewing’s sarcoma (LPPR1::NTRK2), primitive neuroectodermal tumor (DAB2IP::NTRK2), and papillary thyroid carcinoma (RAD51B::NTRK3)." (PMID 38967220, 2024). "The NTRK gene and fusion partner was TPM3::NTRK1 (fibrosarcoma), LPPR1::NTRK2 (Ewing’s sarcoma), DAB2IP::NTRK2 (primitive neuroectodermal tumor), and RAD51B::NTRK3 (PTC)." (PMID 38967220, 2024). "The other two NTRK gene fusions in pediatrics were an LPP1::NTRK2 fusion (Ewing’s sarcoma), and a RAD51B::NTRK3 (PTC); we did not identify ETV6::NTRK3, TPR::NTRK1 – NTRK gene fusions were more commonly reported among pediatrics with solid tumors." (PMID 38967220, 2024).
pleomorphic xanthoastrocytoma (3 papers, 2022 to 2026). A WHO grade ll astrocytic tumor with a relatively favorable prognosis. "In the same study, a case of PA bore a fusion of breakpoint cluster region (BCR) and NTRK2 genes (BCR-NTRK2), while a patient with pleomorphic xanthoastrocytoma (PXA) harbored the tropomyosin 3 (TPM3)-NTRK1 fusion." (PMID 41514664, 2026).
pneumococcal meningitis (3 papers, 2013 to 2022). An acute purulent infection of the meninges and subarachnoid space caused by Streptococcus pneumoniae, most prevalent in children and adults over the age of 60. "In this context it is also notable that Ntrk2 was recently described as a protecting factor in pneumococcal meningitis, making this gene a very promising candidate for further investigation." (PMID 24594938, 2014).
soft tissue tumors (3 papers, 2023 to 2025). "To date, only STRN and RBPMS are identified in the fusion with NTRK2 in adult soft tissue tumors." (PMID 37865792, 2023). "Neurotrophic tyrosine receptor kinase (NTRK)-rearranged spindle cell neoplasms (NTRK-RSCNs) constitute a rare, heterogeneous subset of soft tissue tumors defined by oncogenic fusions involving NTRK1, NTRK2, or NTRK3 genes." (PMID 41409361, 2025). "Neurotrophic tyrosine receptor kinase (NTRK) neoplasms are a rare subset of soft-tissue tumors characterized by gene fusions involving NTRK1, NTRK2, or NTRK3." (PMID 40078480, 2024). "To date, there are approximately 42 partner genes involving NTRK2 rearrangement, and only STRN and RBPMS are identified in the fusion with NTRK2 in adult soft tissue tumors." (PMID 37865792, 2023).
type 2 diabetes (3 papers, 2013 to 2022). "The GMDR has been successful in identifying the significant interaction of CHRNA4 with CHRNB2, NTRK2 with BDNF, and GABBR1 with GABBR2 in nicotine dependence, of LEPR and ADRB2 in obesity, and of HNF4A and KCNJ11 in type 2 diabetes (T2D)." (PMID 23626757, 2013).
adenomyosis (2 papers, 2024). The growth of endometrial tissue inside the muscular wall of the uterine corpus. "Increased expression of BDNF/NT-3 growth factors receptor(NTRK2) in endometrial tissue of patients with adenomyosis during secretion phase." (PMID 39886033, 2024). "Consequently, the excessive generation of NGF in the lesion and the binding of NTRK2 in stromal cells may be connected to the activation of PI3K/AKT in endometrial stromal cells during adenomyosis." (PMID 39886033, 2024).
anaplastic astrocytoma (2 papers, 2022 to 2024). "A tumour with the LHFPL2::NTRK2 fusion in the left temporal lobe of patient #5 (27 y/F) had features of anaplastic astrocytoma with neuropil-like islands, on the basis of the diagnostic criteria of the WHO2016 classification." (PMID 39014476, 2024). "HGAP and PXA were represented by cases with uncharacteristic histology (not clear LGGs), either anaplastic astrocytoma or anaplastic ependymoma, presence of NTRK2 fusions, and long-term survival." (PMID 36163281, 2022).
asthenospermia (2 papers, 2021 to 2024). "Based on transcription combined with GO analysis, NTRK2 may be closely related to male sterility or asthenospermia." (PMID 39769319, 2024).
bronchopulmonary dysplasia (2 papers, 2012 to 2026). Bronchopulmonary dysplasia is a chronic respiratory disease that results from complications related to lung injury during the treatment of infant acute respiratory distress syndrome in low-birth-weight premature infants or from abnormal lung development in older infants. "Downregulated Ntrk2 expression, regulated by miR-29c, may play an important role for the development of hyperoxia-induced bronchopulmonary dysplasia and clearly represents an avenue for further research." (PMID 22646479, 2012). "Our recent work using both human organoid and mouse disease models highlights the non-conventional role of NTRK2 isoforms in regulating pulmonary vasculature and alveolar regeneration during bronchopulmonary dysplasia." (PMID 41852197, 2026).
ependymoma (2 papers, 2022 to 2023). A WHO grade II, slow growing tumor of children and young adults, usually located intraventricularly. "Pathologists reported two cases (KANK1:NTRK2 and RAF1:QKI) as ependymomas, but these tumors were reclassified as low-grade glioma due to the clinical course, underlying molecular alteration, and methylation profile." (PMID 36163281, 2022).